ZNF549 (zinc finger protein 549)
Description:
May be involved in transcriptional regulation.
Synonyms: FLJ34917
Tractability: PROTAC: UniProt records ubiquitination sites on it; ubiquitination databases record sites on it.
Gene: Protein-coding gene on chromosome 19 (57,527,325 to 57,557,542, forward strand). Ensembl gene ENSG00000121406.
Subcellular location: Nucleus
Subcellular location (Human Protein Atlas): Nucleoplasm; Cytosol
Pathways (Reactome):
Gene expression (Transcription): Generic Transcription Pathway
Gene Ontology:
Molecular function: protein binding; DNA-binding transcription factor activity, RNA polymerase II-specific; RNA polymerase II cis-regulatory region sequence-specific DNA binding
Biological process: regulation of transcription by RNA polymerase II; regulation of DNA-templated transcription
Cellular component: nucleus
Genetic constraint (gnomAD): Loss-of-function variants: 11 observed, 11.55 expected, observed/expected ratio (o/e) 0.95, 90% interval 0.6 to 1.56. The upper end of that interval is the gene's LOEUF score, 1.56, which puts it in group 6 of 6, group 1 being the genes least tolerant of losing a copy. Missense variants: 737 observed, 799.15 expected, observed/expected ratio (o/e) 0.92, 90% interval 0.87 to 0.98. Synonymous variants: 259 observed, 281.01 expected, observed/expected ratio (o/e) 0.92, 90% interval 0.83 to 1.02.
Homologues: Orthologues: chimpanzee ZNF549 (99% identical), macaque ZNF549 (96% identical), tropical clawed frog zfx (18% identical), rat Zfy1 (17% identical), mouse Zfy1 (17% identical), mouse Zfy2 (16% identical), zebrafish zfx (16% identical). Paralogues in human: ZNF551 (43% identical), ZNF792 (42% identical), ZNF256 (41% identical), ZNF304 (40% identical), ZNF548 (40% identical), ZNF587B (39% identical), ZNF418 (39% identical), ZIK1 (36% identical), ZNF772 (36% identical), ZNF419 (34% identical), ZNF773 (33% identical), ZNF480 (33% identical), and 26 more.
Diseases named in the same sentence as ZNF549 in open-access papers:
ZNF549 is named in the same sentence as 7 diseases in open-access papers, as found by Europe PMC text mining. Sharing a sentence is not in itself a finding about the gene and the disease. The quoted sentences say what the papers report.
colon adenocarcinoma (2 papers, 2020 to 2023). "Among these predicted miRNAs, hsa_miR‐708‐5p targets ZNF549 in colon cancer to upregulate and inhibit colon adenocarcinoma proliferation and migration via the PI3K/Akt signaling pathway." (PMID 36644969, 2023). "However, the regulating function and mechanisms of ZNF549 in cancer disease, especially colon adenocarcinoma (COAD) remains unclear and highly controversial." (PMID 33028966, 2020).
cancer (2 papers, 2017 to 2020). A tumor composed of atypical neoplastic, often pleomorphic cells that invade other tissues. "RT-qPCR analysis were conducted to detect ZNF549 expression level in 42 paired COAD cancer tissues and matched adjacent tissues, as well as COAD cancer cells (HT29, HCT116, SW480, SW620, and LoVo) and MD2 cell (control)." (PMID 33028966, 2020). "The bisulfite sequencing PCR amplicons of ITGA4 and ZNF549 from non-cancer cell line NP460 and NPC cell line HK1_EBV were also subjected to BGS, and at least five clones were successfully evaluated for all CpG methylation statuses." (PMID 28716111, 2017). "Exploring the anticancer role of ZNF549 in COAD may contribute to the development of novel therapeutic strategies for COAD cancer patients." (PMID 33028966, 2020). "Therefore, ZNF549 can be used as a new molecular biomarker and cancer therapeutic target to improve the prognosis in COAD patients." (PMID 33028966, 2020). "However, ZNF549 involved in cancer occurrence and development have not been reported, especially COAD." (PMID 33028966, 2020).
infection (1 paper, 2021). The state of being infected such as from the introduction of a foreign agent such as serum, vaccine, antigenic substance or organism. "NFE2L2 (Nuclear Factor Erythroid 2-Like 2; OMIM 600492), ZNF250 (Zinc Finger Protein 250) and ZNF549 (Zinc Finger Protein 549) were activated in response to infection (i.e., Herpes Simplex Virus) and inflammation." (PMID 33466592, 2021).
tumor (1 paper, 2020). "In summary, our findings demonstrated that ZNF549, the target gene of miR-708-5p, functions as a tumor suppressor to inhibit COAD cell lines proliferation and migration through regulate the PI3K/AKt signal pathway." (PMID 33028966, 2020).
ZNF549 also shares sentences with these, for which no sentence is quoted: adenocarcinoma (1 paper); colon cancer (1); oropharyngeal cancer (1).